VIM (vimentin)
Diseases named in the same sentence as VIM in open-access papers (continued):
Sharing a sentence is not in itself a finding about the gene and the disease.
breast carcinoma (continued). "Significant correlations between high vimentin tumour cell expression and poor prognosis have previously been reported both in hepatocellular and breast carcinoma." (PMID 18854838, 2008). "Distinct from the two phenotypes above, MDA-MB-231 represents a highly invasive “mesenchymal-like“ breast cancer cell line by expressing a high level of vimentin." (PMID 19113992, 2008). "Vimentin is selectively expressed in invasive human breast cancer cell lines, reflecting the end-stage of tumour de-differentiation." (PMID 17311675, 2007). "In certain carcinomas such as breast cancer or melanoma, vimentin was upregulated in aggressive phenotypes in a phenomenon known as epithelial–mesenchymal transition." (PMID 17325702, 2007). "Since vimentin was atypically expressed in a human breast carcinoma cell line made resistant to doxorubicin, we looked at vimentin expression in these two clones with spontaneously different sensitivity to the drug." (PMID 7880731, 1995). "We discovered an upregulation of PICK1 in VIM‐KO breast cancer cells, suggesting a novel regulatory mechanism whereby VIM may control breast cancer progression through the miR‐615‐3p/PICK1 axis." (PMID 39781570, 2025). "Notably, VIM's overexpression has been correlated with adverse clinical outcomes across a spectrum of cancers, including breast cancer." (PMID 39781570, 2025). "In conclusion, it confirmed that vimentin is involved in the invasion of breast cancer cells." (PMID 39781570, 2025). "Besides ERα, other direct mRNA targets of miRNAs families are ECM‐related molecules, such as IGF‐IR, COL4A1, vimentin, SERPINE1, and ADAM22 mRNAs, all of them associated with breast cancer progression." (PMID 39285617, 2025). "It has been reported that Snail knockdown reduced vimentin expression in breast cancer cell lines." (PMID 40575155, 2025). "Currently, vimentin has been extensively studied in various tumors (including breast cancer)." (PMID 39781570, 2025). "Each of these was supported by (i) the upregulation of KRT18, KRT19, E-cadherin, and downregulation of vimentin in breast carcinoma; (ii) increased levels of GFAP, MAP2, and PSD-95 in astrocytoma; and (iii) increased NeuN, GAP-43, and NF200 levels in neuroblastoma." (PMID 39859209, 2025). "Finally, in highly invasive and metastatic breast cancer cells, the transfection of ARID1A into the cells caused an increase in epithelial marker E-cadherin and a decrease in mesenchymal markers vimentin and N-Cadherin." (PMID 40429787, 2025). "Moreover, vitamin D is able to inhibit invasion and metastasis of breast cancer cells by decreasing N-cadherin and vimentin expression in breast cancer cells while upregulating the expression of E-cadherin." (PMID 40630116, 2025). "It was shown that incubation of MDA-MB-231 breast cancer cells in the presence of fumiquinazoline F resulted in a concentration-dependent increase in the level of E-cadherin and a decrease in the level of vimentin." (PMID 40806710, 2025). "In addition, CAF-CM promoted EMT in breast cancer cells by increasing vimentin and N-cadherin expression and decreasing E-cadherin expression." (PMID 40151143, 2025). "The expression of this molecule has been correlated in breast cancer with recurrence, poor survival and malignancy, as well as decreased expression of E-cadherin and increased expression of vimentin as well as by the expression of β-catenin at the nuclear level that stimulates cell migration." (PMID 38528037, 2024). "In an in vivo investigation using breast cancer orthotopic xenograft tumors, the administration of oleocanthal exhibited the capacity to stabilize E-cadherin while concurrently reducing vimentin expression in recurrent tumors derived from both BT-474 and MDA-MB-231." (PMID 39203892, 2024). "Breast cancers expressing vimentin proteins may originate from progenitor cells with bilinear (glandular and myoepithelial) differentiation potential." (PMID 38903727, 2024).
breast carcinoma (continued). "Ubiquilin2 and myotubularin-1 recognize vimentin for degradation in skeletal muscle cells to avoid proteotoxic aggregate formation.In breast cancer, FERM domain-containing protein 3 (FRMD3) interacts with ubiquitin protein ligase E3A (UBE3A) to induce vimentin proteasomal degradation." (PMID 38383479, 2024). "For instance, lineage tracing techniques showed that vimentin (a classic mesenchymal marker) is not an accurate marker of EMT-associated metastasis in the MMTV-PyMT breast cancer model." (PMID 38324529, 2024). "SLUG and SNAIL increase VIM and drive breast cancer cells toward metastasis." (PMID 40259961, 2024). "Elevated VIM expression indicates aggressiveness and poor prognosis in breast cancer patients." (PMID 40259961, 2024). "In our earlier studies, higher doses of Vitamin D3 were used (up to 1 mM range) and revealed the downregulation of glycolysis and mTOR, as well as the alteration of EMT pathway proteins (Vimentin, E-cadherin, and N-cadherin) and lowering breast cancer cell viability." (PMID 38791386, 2024). "Therefore, E-cadherin, N-cadherin and vimentin are key proteins in EMT of breast cancer cells, and our results have confirmed the regulatory role of SORBS1 on E-cadherin, N-cadherin and vimentin, which is an exciting result." (PMID 38451194, 2024). "Furthermore, The expression level of SLC7A11 has a significant correlation with the expression of vimentin in breast cancer (r = 0.5088, p < 0.0001)." (PMID 39543094, 2024). "Moreover, vimentin plays an important role in the promotion of breast cancer cell migration and invasion." (PMID 37975220, 2024). "Additionally, western blotting results demonstrated that Z-GS suppressed EMT in breast cancer cells by upregulating the epithelial markers E-Cadherin and downregulating the mesenchymal markers N-cadherin and vimentin." (PMID 39543094, 2024). "Moreover, ectopic expression of vimentin is sufficient to induce nuclear dysmorphia in breast cancer MCF7 cells." (PMID 39542246, 2024). "In addition, nodakenin combined with radiation overcomes radioresistance in radioresistant breast cancer cells by suppressing epithelial–mesenchymal transition phenotypes, including the decrease in E-cadherin and the increase in N-cadherin and vimentin." (PMID 36830050, 2023). "During cancer progression, epithelial cells can undergo EMT to migrate, invade, and proliferate and vimentin overexpression can be a sign of the progression of cancerous events, including breast cancer, prostate cancer, endometrial cancer, or gastrointestinal tract tumors." (PMID 37475865, 2023). "Interestingly, CCN3 expression was significantly correlated with vimentin in breast cancer cell lines, which is a mesenchymal marker that has been associated with epithelial to mesenchymal transition (EMT) and metastasis." (PMID 36737605, 2023). "Overexpression of miR-138-5p targets rhomboid domain-containing protein 1 and significantly inhibits the invasion, migration, and epithelial-mesenchymal transition (EMT) of breast cancer cells by upregulating E-cadherin expression and downregulating N-cadherin and vimentin." (PMID 36964570, 2023). "Sections of end-stage tumors from each of the four breast cancer mouse models and normal mammary glands were stained for fibroblasts using antibodies against PDGFRβ, αSMA and vimentin; for collagen fibers by Masson Trichrome and for epithelial cells using antibodies against E-cadherin and EpCAM." (PMID 36635273, 2023). "Furthermore, cells showed an increase in E-cadherin and Zonula occludens-1 (ZO-1) and a reduction in Vimentin and EMT-associated transcription factors Snail1, and Snail2 after C-3-O-G, indicating its activity in reversing EMT in breast cancer cells." (PMID 37190229, 2023). "Clinically, vimentin expression correlates with increased metastatic potential, high nuclear grade, and poor overall survival across most solid tumor types, including lung, prostate, and breast cancers." (PMID 37161053, 2023).
breast carcinoma (continued). "Furthermore, ZEB2‐AS1 expression level, ZEB2, E‐cadherin, and vimentin was measured via qRT‐PCR in 30 paired ductal and lobular carcinoma tissues from breast cancer patients and the normal adjacent ones." (PMID 37088469, 2023). "In addition, THC treatment decreased the expression level of N-Cadherin and vimentin in breast cancer cells and increased the expression level of E-Cadherin." (PMID 36707875, 2023). "Resistance-associated proteins were Caveolin-1, PgR, mTOR, phosphorylated MEK1/2 (pSer217/221) of the Erk/MAPK signaling pathway, phosphorylated IKKα (pThr23) of the NFκB pathway, the microtubule-associated protein Tau and the basal breast cancer markers CK5, CK6 and Vimentin-pSer56." (PMID 37596623, 2023). "While other EMT-related genes (e.g., SNAI1 and VIM) are highly coexpressed, ESR1 (Estrogen Receptor alpha) is one of the top anticorrelated genes, in agreement with the FOSL1-associated mesenchymal features of triple-negative (and basal-like) breast cancers." (PMID 37176013, 2023). "Here, we proposed that FRMD3 could inhibit the adhesion and motility of breast cancer cells by inducing the ubiquitination and degradation of vimentin, an essential regulator of cancer metastasis." (PMID 36631457, 2023). "In this study, we demonstrated that FRMD3, which is significantly downregulated in breast cancer, binds with vimentin through its ubiquitin-like domain, leading to the ubiquitination-mediated degradation of vimentin via recruiting ubiquitin ligase UBE3A in breast cancer cells." (PMID 36631457, 2023). "Vimentin drives EMT and metastasis in several solid cancers; upregulation of Vimentin is associated with poor clinical outcome in several cancers as acute myeloid leukemia, breast cancers and oral squamous cell carcinomas." (PMID 35054891, 2022). "We found SEC61G downregulation could remarkably weaken N-cadherin and Vimentin expression and enhance E-cadherin expression in breast cancer cells." (PMID 35154452, 2022). "Thus, low expression of miR-200b/c induces increased expression of ZEB1/2 and vimentin, which is effective in increasing metastasis and invasion of breast cancer cells, and on the other hand, inhibits the function of Tamoxifen." (PMID 35928368, 2022). "Vimentin levels are higher in TNBC relative to other breast cancer subtypes." (PMID 36494865, 2022). "In addition, STAT3 was reported to be activated by inflammatory cytokines, such as IL6, IL8 and TNFα, which enhance breast cancer proliferation, invasion and metastasis through the upregulation of Twist, Snail, Slug, Vimentin and HIF-1α." (PMID 35747796, 2022). "Then, we analyzed by western blotting the expression of EMT markers which showed a decrease in the expression of epithelial markers (E-cadherin and occludin) and an increased expression of mesenchymal markers (vimentin and N-cadherin) in Elovl5-silenced breast cancer cells." (PMID 36056008, 2022). "Collectively, we demonstrate, for the first time, that vimentin in breast cancer cells could change nuclear architecture by affecting lamin expression, which downregulates genes maintaining cell–cell junctions resulting in increased cell migration." (PMID 36552797, 2022). "The expression of vimentin and Ki-67 may indicate that the long-term prognosis of ER-positive tumors is poor, and studies have shown that vimentin is positively correlated with the expression of ER in breast cancer." (PMID 35992122, 2022). "Moreover, the expression levels of GPR110 and EMT signature gene (Slug or Vimentin) were positively correlated with each other in patients from the TCGA breast cancer clinical cohort." (PMID 35614051, 2022). "For example, CPEB4 can regulate tumour cell invasion and migration by regulating Vimentin expression in breast cancer; ZEB1-mediated EMT may be involved in CPEB4-promoted cell proliferation, invasion, and metastasis in gastric cancer." (PMID 35317822, 2022).
breast carcinoma (continued). "In order to determine whether the most active complexes (1 and 6) were able to regulate the vimentin expression in the adopted breast cancer cells, we used immunofluorescence analyses." (PMID 35631334, 2022). "Proteins, such as Mortalin and Vimentin, which contribute to this early pathological migration and invasion process may be critical molecular targets for early breast cancer metastasis intervention." (PMID 35915218, 2022). "However, it is worth mentioning that downregulation of ECAD and upregulation of SNAIL and VIM are associated with EMT stress adaptation in esophageal and breast cancer." (PMID 36555289, 2022). "To determine whether SPOP could affect EMT, we silenced SPOP in both BT549 and T47D breast cancer lines and examined the effects on E-cadherin, Vimentin and N-cadherin by Western blotting." (PMID 36115849, 2022). "In the present study, we evaluated mRNA expression patterns of the mitotic kinases Nek2, Mps1/TTK, and TBK1, as well as the expression and association of these proteins with biomarkers of proliferation (Ki67) and EMT (E-cadherin and Vimentin) by using a novel breast cancer TMA." (PMID 36494865, 2022). "In addition to KLF5, AXL is an EMT-induced regulator of cancer metastasis, controlled by Slug and Vimentin in breast cancer." (PMID 36042208, 2022). "In this work, we found that vimentin overexpression itself rendered MDA-MB-231 breast cancer cells resistant to chemotherapeutic agents, while vimentin knockdown rendered cells more sensitive to the drugs, indicating the involvement of vimentin in drug resistance." (PMID 34203746, 2021). "In consequence, the stem cell traits acquired during EMT were partially reversed once accompanied by HRD1 overexpression, suggesting that HRD1-induced decline of Vimentin stability could prevent the generation of metastatic breast cancer stem cells (BCSCs)." (PMID 33530981, 2021). "Similarly, SALL1 knockdown led to the differential expression of EMT markers, such as E-cadherin and vimentin in SUM149 breast cancer cells, leading to increased cell migration in vitro." (PMID 34944911, 2021). "Interestingly, it was shown that overexpression of TRPM8 induced EMT in breast cancer cells by upregulating vimentin and fibronectin while downregulating E-cadherin." (PMID 34360952, 2021). "Notably, with the treatment of CTI-2 in breast cancer cells, the expression level of E-cadherin increased, while the expression level of N-cadherin and vimentin decreased." (PMID 34830111, 2021). "Indeed, a subpopulation of tumor cells has been previously observed with co-expression of vimentin and keratin in colorectal cancer patients (“tumor budding”), as well as from metastatic cancer cells in breast cancer patients." (PMID 33691719, 2021). "The vimentin promoter is mentioned as a possible target for the β-catenin/TCF pathway in order to enhance cell motility during EMT by increasing the vimentin expression in breast cancer cells." (PMID 34638469, 2021). "Studies have also demonstrated that knockdown of vimentin resulted in downregulation of genes involved in breast cancer invasion and the basal-like phenotype, including Axl, ITGB4, and PLAU, with a subsequent upregulation in the genes abundant in normal mammary epithelium, including RAB25 and EHF." (PMID 34769002, 2021). "It was also noted that ectopic expression of FBXL14 reduced vimentin level in breast cancer cells." (PMID 33801272, 2021). "Similarly, withaferin A, a natural product, can also interact with vimentin to inhibit both breast cancer cell growth and neovascularization in vivo." (PMID 34203746, 2021). "However, accompanied with recent research revealing the inhibitory effect of HRD1 on TNBC tumorigenesis, from the perspective of our research, HRD1 plays a role of tumor suppressor due to its anti-metastasis activity targeting Vimentin in breast cancer." (PMID 33530981, 2021).
breast carcinoma (continued). "This may be one of the reasons why increasedexpression of VIM in breast cancer contributes tochemoresistance and poor prognosis." (PMID 31606974, 2020). "After upregulating miR-532-3p expression, the epithelial mark (E-ca) was again reduced, while mesenchymal markers including N-ca and Vimentin proteins, were consistently increased in OE_ circRNA_103809 breast cancer cells, in both circRNA_103809-overexpressed MDA-MB-157 and MDA-MB-231 cells." (PMID 32499818, 2020). "In mice with hyperinsulinemia with breast cancer, vimentin knockdown decreased pulmonary metastasis showing that vimentin could be a target in patients with obesity or diabetes." (PMID 33171868, 2020). "In addition, it has been reported that upregulation of miR-7 and miR-185 contributed to a similar outcome where miR-7 was negatively correlated with vimentin mRNA levels in breast carcinoma tissues by inhibiting EMT via focal adhesion pathway." (PMID 33374139, 2020). "Conversely, knock-down of TUSC8 up-regulated the expression of mesenchymal related markers (ZEB1, TWIST, SNAI1 and Vimentin), and down-regulated the expression of epithelial related marker (E-cadherin) in breast cancer cell lines MCF-7 and HCC1937 (p < 0.05, p < 0.01 respectively)." (PMID 32039833, 2020). "It is known that vimentin may interact with p62 in breast cancer cells and that this interaction promotes metastasis." (PMID 32286254, 2020). "The western blot and the band intensity analysis hinted that over-expression of TUSC8 down-regulated the expression of mesenchymal related markers (ZEB1, TWIST, SNAI1 and Vimentin) in breast cancer cell lines SK-BR-3 and MDA-MB-435 (p < 0.05, p < 0.01 respectively)." (PMID 32039833, 2020). "In addition, we noted a significant increase in the number of vimentin-positive breast cancer cells in BT-474/CO group as compared to BT-474/CTRL one (p = 0.044)." (PMID 32498363, 2020). "In addition, an in vitro experiment for demonstrating the co-expression of nBMP-2 and RANKL or vimentin or SDF-1 in breast cancer cells that acquire the capability to produce microcalcifications was developed." (PMID 32498363, 2020). "Leptin decreased E-cadherin expression and increased vimentin expression in breast cancer cells." (PMID 32836215, 2020). "Besides, the increase phenotype in invasive capacity of MDA-MB-231 by overexpression of p62 is dependent on Vimentin levels, demonstrating Vimentin plays a crucial role in p62-mediated invasion in breast cancer cells." (PMID 33634029, 2020). "In our study, we found that E‐cadherin and EMT markers were co‐expressed in a variety of human breast cancer cells, and expression in luminal subtype tumours was higher compared with basal‐like breast cancers, while Vimentin, Snail and Slug were more highly expressed in basal‐like breast cancers." (PMID 32510753, 2020). "However, in several cancers, such as breast cancer and melanoma, intermediate filaments including cytokeratin and vimentin are co-expressed together in the tumour cells." (PMID 31963677, 2020). "CLEC2B, HLA-E, IL15, and VIM all appear in the 4 subtypes at the same time, which may mean that they play a more general role in different subtypes of breast cancer." (PMID 33304391, 2020). "In this context, vimentin expression is regulated by Slug in breast cancer models." (PMID 32545405, 2020). "Furthermore, co-culture with CD133+ HPCs, enhanced the invasion of breast cancer cells, N-cadherin and Vimentin expression, but reduced E-cadherin expression in breast cancer cells." (PMID 33243165, 2020). "Furthermore, expression of N-cadherin as well as the epithelial markers CK18 and CK19 in PMNs was higher in breast cancer patients than in HVs, implying that N-cadherin is expressed mainly in CTCs, similar to vimentin." (PMID 31947504, 2020).